IGHV3-16 (immunoglobulin heavy variable 3-16 (non-functional))
Description:
Probable non-functional open reading frame (ORF) of V region of the variable domain of immunoglobulin heavy chains. Non-functional ORF generally cannot participate in the synthesis of a productive immunoglobulin chain due to altered V- (D)-J or switch recombination and/or splicing site (at mRNA level) and/or conserved amino acid change (protein level). Immunoglobulins, also known as antibodies, are membrane-bound or secreted glycoproteins produced by B lymphocytes. In the recognition phase of humoral immunity, the membrane-bound immunoglobulins serve as receptors which, upon binding of a specific antigen, trigger the clonal expansion and differentiation of B lymphocytes into immunoglobulins-secreting plasma cells. Secreted immunoglobulins mediate the effector phase of humoral immunity, which results in the elimination of bound antigens. The antigen binding site is formed by the variable domain of one heavy chain, together with that of its associated light chain. Thus, each immunoglobulin has two antigen binding sites with remarkable affinity for a particular antigen. The variable domains are assembled by a process called V-(D)-J rearrangement and can then be subjected to somatic hypermutations which, after exposure to antigen and selection, allow affinity maturation for a particular antigen.
Synonyms: IGHV316; VH
Gene: Immunoglobulin variable (V) gene on chromosome 14 (106,165,205 to 106,165,730, reverse strand). Ensembl gene ENSG00000211944.
Subcellular location: Secreted; Cell membrane
Gene Ontology:
Molecular function: antigen binding
Biological process: immunoglobulin mediated immune response
Cellular component: extracellular region; plasma membrane
Homologues: Paralogues in human: IGHV3-35 (91% identical), IGHV3-23 (77% identical), IGHV3-48 (77% identical), IGHV3-64 (77% identical), IGHV3-74 (77% identical), IGHV3-11 (76% identical), IGHV3-7 (76% identical), IGHV3OR16-13 (76% identical), IGHV3-20 (75% identical), IGHV3-21 (75% identical), IGHV3-43 (75% identical), IGHV3-66 (75% identical), and 65 more.